CHRNA1 (cholinergic receptor nicotinic alpha 1 subunit)
Diseases named in the same sentence as CHRNA1 in open-access papers:
CHRNA1 is named in the same sentence as 53 diseases in open-access papers, as found by Europe PMC text mining. Sharing a sentence is not in itself a finding about the gene and the disease. The quoted sentences say what the papers report.
congenital myasthenic syndrome (11 papers, 2013 to 2025). Congenital myasthenic syndrome (CMS) is a group of genetic disorders of impaired neuromuscular transmission at the motor endplate characterized by fatigable muscle weakness. "Mutations in CHRNA1 are responsible for postsynaptic congenital myasthenic syndromes (CMS) and occur either as slow-channel syndrome or fast-channel syndrome." (PMID 39677241, 2024). "Here, we report on a CHRNA1 mutation (α1Leu251Arg) in a patient with congenital myasthenic syndrome associated with transformation of the muscle acetylcholine receptor (AChR) into an inhibitory channel." (PMID 31570625, 2019). "In congenital myasthenic syndrome, the aberrant inclusion of muscle nicotinic acetylcholine receptor α subunit (CHRNA1) exon P3A is caused by an intronic mutation." (PMID 24264039, 2013). "In some cases, treatments such as acetylcholinesterase inhibitors may be considered, particularly in patients with pathogenic variants in congenital myasthenia genes (CHRNA1, CHRND, DPAGT1, and GFPT1)." (PMID 38982518, 2024). "Mutations in CHRNA1 and CHRNA6 have been implicated in fast-channel congenital myasthenic syndrome (MIM#608930) characterized by early-onset progressive muscle weakness and chronic pain." (PMID 36375841, 2023). "Moreover, four families with CM carried pathogenic variants in GFPT1, CHRNA1, or CHRND, all three previously associated with congenital myasthenia often involving muscle weakness similar to CM." (PMID 38982518, 2024). "Mutations in CHRNA1 have been associated with congenital myasthenic syndromes (OMIM#100690), not present in this pedigree." (PMID 31525280, 2020).
lung carcinoma (10 papers, 2009 to 2023). "Seven SNPs in three nAChR genes were significantly associated with lung cancer at a strict Bonferroni-corrected level, including a novel association on chromosome 2 near the promoter of CHRNA1 (rs3755486: OR = 1.40, 95% CI = 1.18-1.67, P = 1.0 × 10−4)." (PMID 23232035, 2012). "Located <3kb upstream of CHRNA1, rs3755486 showed a strong association with lung cancer risk (OR = 1.40, 95% CI = 1.18-1.67, P = 1.0 × 10−4)." (PMID 23232035, 2012). "Studies conducted in additional ancestral populations will help to determine if CHRNA1 SNPs confer lung cancer risk in multiple ethnicities, or if the effects identified here are specific to African-Americans." (PMID 23232035, 2012). "The lung cancer risk allele was associated with increased levels of CHRNA1 expression." (PMID 23232035, 2012). "How risk alleles near the CHRNA1 gene promoter may influence lung cancer incidence in African-Americans is particularly intriguing, as the allele identified as a novel risk factor tends to be more common in European populations." (PMID 23232035, 2012). "Furthermore, PIK3C2G, FIBIN, CHRNA1, NPNT, MEOX1, and POU2F2 linked obesity and lung cancer, while PTPRQ, SSUH2, CILP2, CDH2, ABCA12, CPXM1, and L1CAM linked hypertension and lung cancer." (PMID 36685671, 2023). "CHRNA1, a neuromuscular nAChR subunit gene, has not been previously associated with lung cancer risk or with smoking behaviors." (PMID 23232035, 2012).
myasthenia gravis (8 papers, 2012 to 2024). Myasthenia gravis (MG) is a rare, clinically heterogeneous, autoimmune disorder of the neuromuscular junction characterized by fatigable weakness of voluntary muscles. "It was reported that the polymorphisms in the promoter region of the muscle acetylcholine receptor gene (CHRNA1), which is associated with the early onset of human autoimmune myasthenia gravis, leads to the reduction of CHRNA1 expression in human mTECs." (PMID 22969770, 2012). "The major autoantibody target, found in approximately 85% of myasthenia gravis patients, is the extracellular N-terminal region of the alpha 1 subunit of the nicotinic acetylcholine receptor/nAChR (CHRNA1), which is highly enriched in skeletal muscle." (PMID 33763057, 2021). "In contrast, genes coding for the acetylcholine receptor (CHRNA1), the muscle antigen titin (TTN), and MUSK, which are associated with the neuromuscular autoimmune disease myasthenia gravis, were predominantly found in the myoid, neuroendocrine, and ciliated subsets." (PMID 33597545, 2021). "CHRNA1 homeostasis is vital for postsynaptic signal regulation, and altered CHRN endocytosis mediated by carbonic anhydrase 3 might contribute to the pathogenesis of myasthenia gravis." (PMID 37542348, 2023). "Other interesting data were the lower gene levels for some of the components of the acetylcholine receptor (CHRNB1, CHRNA1 and CHRNG) that may result in a significant reduction of the amplitude of the transmission signal, as has already been demonstrated for myasthenia gravis patients." (PMID 36359747, 2022).
diabetes (4 papers, 2008 to 2019). "Chrna1 (cholinergic receptor, nicotinic, alpha 1) and Rrad (Ras-related associated with diabetes), genes whose expression levels are upregulated by denervation and in SOD1G93A animals, were not significantly affected by 5-FU." (PMID 30640943, 2019). "To determine the effect of BMC grafts on the NMJs, we quantified transcript levels of Ras-related associated with diabetes (Rrad), cholinergic receptor, nicotinic, alpha 1 (Chrna1) and Reticulon-4 (NogoA), a well-known inhibitor of axonal regeneration and promoter of NMJ destruction." (PMID 29625589, 2018). "We sequenced CHRNA1, CHRND and CHRNG in 24 Amish subjects from the Amish Family Diabetes Study (AFDS) and identified 20 variants." (PMID 18625075, 2008). "Myocardial down-regulation of Chrng and Chrna1 demonstrated in our present study might be another factor of cardiac autonomic dysfunction in diabetes." (PMID 27496100, 2016).
multiple pterygium syndrome (3 papers, 2022 to 2024). "Recessive mutations in the CHRNA1 gene result in lethal multiple pterygium syndrome (LMPS; OMIM# 253290)." (PMID 36900003, 2023). "A repeatedly reported phenotypic feature of CHRNA1 mutations that did not occur in the index patient is fatal multiple pterygium syndrome." (PMID 39677241, 2024).
glioma (2 papers, 2016 to 2021). A benign or malignant brain and spinal cord tumor that arises from glial cells (astrocytes, oligodendrocytes, ependymal cells). "To investigate the clinical importance of nAChRs in gliomas, we examined clinical outcomes and found that glioma patients with tumors overexpressing CHRNA1 or CHRNA9 (encoding for the AChR-α1 or AChR-α9) exhibit significant shorter overall survival." (PMID 26575950, 2016). "We identified CHRNA1 and CHRNA9, two alpha subunits of the AChR complex, to be upregulated in glioma with strong association between expression and patient survival." (PMID 26575950, 2016). "This analysis revealed that survival of patients with tumors overexpressing CHRNA1 or CHRNA9, which are both expressed in all our GSC lines, is significantly shorter as compared to all gliomas (n = 343)." (PMID 26575950, 2016).
Hyperhidrosis (2 papers, 2023 to 2025). Abnormal excessive perspiration (sweating) despite the lack of appropriate stimuli like hot and humid weather. "Using both clinical samples and experimental models, we further confirmed that rhPAI-1 intervention downregulated CHRNA1 expression and ameliorated the hyperhidrosis phenotype, suggesting a critical regulatory role of PAI-1 in PFH pathogenesis." (PMID 40503176, 2025). "PAI1 inhibits CHRNA1-mediated hydrochloride-induced hyperhidrosis, with decreased sweat gland secretion and diminished ACH, AQP5, and CACNA1C expression." (PMID 37542348, 2023). "Pai1 knock-out mice demonstrated up-regulated expression of CHRNA1 in both mRNA and protein levels after hyperhidrosis induction." (PMID 37542348, 2023). "Cisatracurium (CIS, antagonist of CHRNA1) or PAI-039 (small-molecule inhibitor of PAI1) was pre-administrated before the induction of hyperhidrosis." (PMID 37542348, 2023). "Further understanding of CHRNA1 homeostasis-mediated by PAI1 will shed light on the pathogenesis of hyperhidrosis." (PMID 37542348, 2023). "Pai1 knock-out mice demonstrated increased numbers of black dots, while such phenomenon could be prohibited by the administration of CIS, which indicated that PAI1 could negatively regulate CHRNA1-mediated hyperhidrosis." (PMID 37542348, 2023). "In our previous research, small-interfering RNA targeting Chrna1 could attenuate the pathogenesis of pilocarpine-induced hyperhidrosis in mice." (PMID 37542348, 2023). "On the other hand, transgenic Pai1 could inhibit the development of hyperhidrosis with decreased CHRNA1 expression, and the alleviation of hyperhidrosis phenotype could be restored by the administration of Chrna1-expressing AAV." (PMID 37542348, 2023). "PAI1 inhibition with PAI-039 or Pai1 deficiency could induce up-regulated CHRNA1, ACH, AQP5, and CACNA1C expression and sweat secretion in hydrochloride-induced hyperhidrosis mice." (PMID 37542348, 2023). "Our findings demonstrate that PAI1 could target CHRNA1-mediated hydrochloride-induced hyperhidrosis in mice." (PMID 37542348, 2023). "Our results indicate that PAI1 could prohibit CHRNA1-mediated hydrochloride-induced hyperhidrosis." (PMID 37542348, 2023). "Functionally, rhPAI-1 administration reduced sweat secretion and serum acetylcholine levels in a pilocarpine-induced hyperhidrosis mouse model, supporting the therapeutic potential of targeting the PAI-1/CHRNA1 pathway in PFH." (PMID 40503176, 2025). "Plasminogen activator inhibitor-1 (PAI1, encoded by SERPINE1) is reported to inhibit the expression of CHRNA1, while the role of PAI1 in hyperhidrosis is unknown." (PMID 37542348, 2023). "PAI-039 could up-regulate the relative expression of CHRNA1 in both mRNA and protein levels in hydrochloride-induced hyperhidrosis mice, while PAI-039 did not alter the relevant CHRNA1 expression in normal mice without hydrochloride stimulation." (PMID 37542348, 2023). "Although the detailed or precise mechanism of PAI1-mediated CHRNA1 inhibition is not deciphered in this study, our investigation further indicates that PAI1-mediated endocytosis may affect CHRNA1 homeostasis in hyperhidrosis." (PMID 37542348, 2023).
thymoma (2 papers, 2022 to 2023). A neoplasm arising from the epithelial cells of the thymus. "Accordingly, lower CHRNA1 mRNA levels were associated with significantly reduced AIRE mRNA levels in our MG thymoma samples, and with slightly reduced AIRE mRNA levels in hyperplastic MG thymuses." (PMID 36979710, 2023). "Similarly to CHRNA1, genes encoding for the two thymoma-associated autoantigens RYR1 and TTN were expressed at lower levels in MG compared to non-MG thymomas, with RYR1 being mainly down-regulated in the MG A/AB subset, and TTN in the MG A/AB and B3/B3 mixed subset." (PMID 36979710, 2023). "The AIRE mRNA levels positively correlated with those of CHRNA1 in hyperplastic thymuses and thymomas from untreated MG patients (Pearson r = 0.83 and p < 0.0001; data not shown)." (PMID 36979710, 2023). "Of note, reduced intra-thymic CHRNA1, as well as AIRE, mRNA levels were observed in both corticosteroid-naïve and -treated MG thymoma patients, but only in corticosteroid-naïve patients with follicular hyperplastic thymuses." (PMID 36979710, 2023). "A significant reduction in CHRNA1 expression was also observed in MG thymomas, particularly in thymomas from corticosteroid-naïve patients, compared to non-MG thymomas and control thymuses." (PMID 36979710, 2023). "Taken together, these data suggest that a lower CHRNA1 and AIRE expression in MG thymuses, particularly thymomas, could signify relevant molecular alterations contributing to anti-AChR autosensitization." (PMID 36979710, 2023). "Of interest, we found lower expression levels of CHRNA1 in both hyperplastic and thymoma MG thymuses, particularly type B1/B2 MG thymomas, compared to normal thymuses and non-MG thymomas." (PMID 36979710, 2023). "Indeed, we found a positive correlation between CHRNA1 and AIRE expression levels in both hyperplastic thymuses and thymomas." (PMID 36979710, 2023). "To further address the question whether the intra-thymic expression of muscle autoantigens is altered in AChR-MG patients, we searched for possible changes in the CHRNA1, RYR1, and TTN expression levels, in relationship with AIRE expression, in hyperplastic MG thymuses and MG thymomas." (PMID 36979710, 2023). "Since CHRNA1 expression is controlled by AIRE, which is defective in thymomas, a reduction in CHRNA1 expression rather than an increase in these pathological tissues could be expected." (PMID 36979710, 2023). "The autoantibody titer did not correlate with the expression levels of CHRNA1, NEFM, and HSP60 in follicular hyperplastic and thymoma MG thymuses." (PMID 36979710, 2023). "Liu and colleagues reported a lower CHRNA1 and AIRE expression in MG thymomas, mainly of types B2 and B3, compared to non-MG thymomas." (PMID 36979710, 2023). "Transcriptional levels of CHRNA1, RYR1, and TTN autoantigen genes were assessed in hyperplastic and thymoma thymuses of MG patients, non-MG thymomas, and normal thymuses using real-time PCR." (PMID 36979710, 2023). "We found that CHRNA1 (AChR-α subunit) and AIRE (autoimmune regulator) genes were expressed at lower levels in hyperplastic and thymoma MG compared to the control thymuses, and that the RYR1 and TTN levels were decreased in MG versus the non-MG thymomas." (PMID 36979710, 2023).
deafness (1 paper, 2020). An inherited or acquired condition characterized by the complete loss of the ability to hear from one or both ears. "The list includes one known deafness gene, Ptprq, as well as Chrna1, which is expressed in the organ of Corti from early postnatal stages onwards." (PMID 33318051, 2020).
Escobar syndrome (1 paper, 2022). "While CHRNG mutations caused Escobar syndrome for 75 patients of known cases, a number of patients had a genetic etiology associated with variants in the TPM2, CHRND, CHRNA1, MUSK, MYH3, RAPSN, and DOK7 genes." (PMID 36292632, 2022). "Indeed, mutations in CHRNA1, CHRND, and TPM2 have been described to be associated with Escobar syndrome." (PMID 36292632, 2022).
Headache (1 paper, 2022). Cephalgia, or pain sensed in various parts of the head, not confined to the area of distribution of any nerve. "In this cohort, there were only correlations of CHRM4-Ab with immune symptoms and of ADRB1- and CHRNA1-Ab correlated with headache." (PMID 36238301, 2022).
lung adenocarcinoma (1 paper, 2021). A carcinoma that arises from the lung and is characterized by the presence of malignant glandular epithelial cells. "The high expression of CHRNA1 is related to the low postoperative survival probability in early lung adenocarcinoma." (PMID 34912722, 2021).
myasthenia (1 paper, 2026). "Although most of the patients with mutations in established CMS genes (such as DOK7, MUSK, RAPSYN, CHRNA1, CHRNB1, CHRND, and CHRNE) do not show cognitive symptoms, in some newly identified CMS subtypes, myasthenia is only one element of a more severe and complex clinical spectrum." (PMID 41575592, 2026).
ptosis (1 paper, 2022). The drooping of the upper eyelid. "Most of these CMS are accompanied by additional features such as dysmorphism (CHRNA1), or limb-girdle pattern of weakness (GFPT1; GMPPB; DGPAGT1) without EOM weakness or ptosis." (PMID 35280301, 2022).
tumor (4 papers, 2016 to 2022). "It has been found that nAChR subunits displayed different protein expression in different tumour sites promoting tumour progression, such as CHRNA1, which increased protein expression in the hypopharynx, larynx, and advanced tumours, but decreased in oropharynx tumours." (PMID 32455963, 2020). "However, we did find the expression of CHRNA1, CHRNA9, and CHRNB1 to be significantly upregulated in the GBM samples in comparison to the non-tumor samples." (PMID 31590360, 2019). "Finally, we found that ex-vivo pre-treatment of GSCs, expressing CHRNA1 and CHRNA9, with Atracurium Besylate significantly increased the survival of mice xenotransplanted with these cells, therefore suggesting that tumor initiating subpopulations have been reduced." (PMID 26575950, 2016).
infection (2 papers, 2022 to 2023). The state of being infected such as from the introduction of a foreign agent such as serum, vaccine, antigenic substance or organism. "After adjustment for the potential confounders, sex, age, and time since infection, we found in addition to CHRM5-Ab significant differences with higher levels of AABs against CHRM1 and F2R/PAR-1 while lower levels of ADRB1, CHRNA1, and EDNRA in PCS/ME/CFS than in PCS/non-ME/CFS groups." (PMID 36238301, 2022).
myopathy (1 paper, 2024). A disease of the muscle in which the muscle fibers do not function properly. "The top five up-regulated genes in general myopathy are MGST1, AOX1, FASN, PRKCD, and CHRNA1, which have been rarely reported in previous myopathy studies." (PMID 38600180, 2024).
CHRNA1 also shares sentences with these, for which no sentence is quoted: cancer (4 papers); nicotine addiction (3); arthrogryposis (2); lethal multiple pterygium syndrome (2); schizophrenia (2); Airway obstruction (1); anorexia nervosa (1); autoimmune disease (1); autonomic dysfunction (1); brain malformations (1); breast carcinoma (1); cardiac hypertrophy (1); channelopathies (1); chronic bronchitis (1); chronic obstructive pulmonary disease (1); congenital muscular dystrophy (1); congenital myopathy (1); depression (1); distal myopathy (1); emphysema (1); epilepsy (1); hepatocellular carcinoma (1); Hypertension (1); Intellectual disability (1); lung disorder (1); melanoma (1); myofibrillar myopathy (1); Myotonia (1); Neurologic Disease (1); Obesity (1).
A further 6 diseases each share a sentence with CHRNA1 in 1 paper.